NF2 (NF2, moesin-ezrin-radixin like (MERLIN) tumor suppressor)
Diseases named in the same sentence as NF2 in open-access papers (continued):
Sharing a sentence is not in itself a finding about the gene and the disease.
meningioma (continued). "NF2 gene alterations, that is 22q loss and/or NF2 mutation, are the most common genetic driver events in meningioma and are associated with tumour location, histological subtype and aggressiveness." (PMID 40815185, 2025). "NF2 alteration has been recognized as an important factor for molecular subgrouping of meningiomas, and it is potentially a useful diagnostic and prognostic marker." (PMID 40815185, 2025). "Dual blockade of mTORC1/2 and IGF1R/insulin signaling effectively reduced pAkt T308 and cell viability, supporting co-inhibition as a potential therapeutic strategy in NF2-deficient meningiomas." (PMID 41200151, 2025). "Complete loss of Merlin expression was observed in 46 of 51 (90%) meningiomas with NF2 alterations, whereas it was observed in 5 of 58 (9%) meningiomas without NF2 alterations." (PMID 40815185, 2025). "Deletion in 22q and mutations in the neurofibromatosis type 2 (NF2) gene are frequent in sporadic meningiomas." (PMID 40447281, 2025). "Major criteria include unilateral vestibular schwannoma, a first-degree relative other than a sibling with NF2, 2 or more meningiomas, and NF2 pathogenic variant in an unaffected tissue." (PMID 40713130, 2025). "The molecular characterization of meningiomas has led to the identification of key tumor-driving mutations, including NF2, POLR2A, TRAF7, KLF4, AKT1, SMARCB1, SMARCE1, and SMO." (PMID 39941893, 2025). "Meningiomas can therefore be classified as either non-NF2-mutated or NF2 (neurofibromatosis type 2)." (PMID 40423252, 2025). "Psammoma bodies, which appear as concentric, lamellated, and calcified structures within a tumor, are among the most salient features observed in NF-2 mutation-associated meningiomas." (PMID 38611661, 2024). "We characterized NF2‐associated meningioma‐infiltrated lymphocytes using immunohistochemical staining with a specific antibody." (PMID 38828669, 2024). "Copy-number variations (CNVs) in meningioma have been studied for decades: > 50% of meningioma show 22q loss, the chromosomal arm that harbors the NF2-gene." (PMID 39115604, 2024). "The results also showed that all of the NF2‐associated meningiomas had CD3‐ and CD8‐positive T lymphocytes (13/13, 100%), which are considered indicators of a good PD‐L1 therapy response, providing a foundation for anti‐PD‐L1 therapy." (PMID 38828669, 2024). "NF2, when mutated, accounts for the inherited genetic disorder Neurofibromatosis type 2, which leads to the development of schwannomas and meningiomas in patients." (PMID 39273576, 2024). "NF2‐associated meningiomas frequently show aggressive clinical features and can cause serious neurological deficits." (PMID 38828669, 2024). "After PD‐L1 knockdown in NF2‐associated meningioma cells, tumor cell proliferation was significantly inhibited, and the apoptosis rate was elevated." (PMID 38828669, 2024). "The primary mutation leading to meningioma development is often the loss of chromosome 22, resulting in the loss of the NF2 gene, which inhibits tumor formation (OMIM 607379)." (PMID 39022728, 2024). "The mean age of the cohort was 52.9 ± 13.9 for patients with meningiomas with NF-2 mutations data and 52.3 ± 13.8 for those with S100 protein expression data." (PMID 38611661, 2024). "The inactivation, mutation, or loss of NF2 in meningiomas leads to loss of NF2 tumor suppressor activity, most notably by way of altered E-Cadherin expression, CD44-mediated cell–cell contact inhibition, and the Hippo signaling pathway." (PMID 39796693, 2024). "NF2 patients also display an elevated risk of developing schwannomas at other locations or brain tumours of different varieties (i.e., meningiomas and ependymomas)." (PMID 38338806, 2024). "The results show that the expression of β‐TrCP decreases in NF2‐associated meningioma cells after treatment with rapamycin (2 μmol/L 48 h), suggesting that the stability of PDL1 can also be regulated by inhibiting the mTOR pathway." (PMID 38828669, 2024).
meningioma (continued). "Other tyrosine kinase inhibitors that have also been explored in NF2-associated schwannomas and meningiomas include crizotinib, brigatinib, and dasatinib." (PMID 39935847, 2024). "EPHB1 and EPHB3 are overexpressed in rhabdomyosarcoma tumor cells, while EPHB2 high-level expression has been reported in medulloblastoma tumor tissue samples, in NF2-deficient meningioma cell lines, and rhabdomyosarcoma tumor cells." (PMID 38612645, 2024). "Cancer gene panel testing of the present retroperitoneal tumor revealed a deletion of exons 5–9 in NF2, in accordance with previous reports revealing NF2 mutations in both meningiomas and perineuriomas." (PMID 38739347, 2024). "Bi-allelic loss of the tumor suppressor NF2 is associated with approximately one-half of sporadic meningiomas and most syndromic cases." (PMID 38730704, 2024). "The results showed the presence of CD4‐positive T lymphocytes (3/13, 23.08%) and CD20‐positive B lymphocytes (6/13, 46.15%) in NF2‐associated meningiomas." (PMID 38828669, 2024). "We and others have previously shown that NF2-deficient schwannomas and meningiomas responds to PAK inhibitors in vivo." (PMID 39083549, 2024). "Inactivating mutations of the NF2 gene are found in approximately 50% of meningiomas across all WHO grades." (PMID 39273576, 2024). "Specific mutations, such as those in the NF2 gene, are more frequently observed in higher-grade meningiomas and are slightly more common in men, suggesting a genetic basis for the observed differences in tumor aggressiveness." (PMID 39188673, 2024). "Loss of PAK function, in particular the PAK1 isoform, is associated with slower growth of NF2-deficient meningioma and schwannoma cells and has been proposed as a plausible therapeutic target for these tumors." (PMID 39083549, 2024). "The progressive accumulation of chromosomal losses and gains leads to meningioma progression, and monosomy of chromosome 22q is believed to be an early event in the pathogenesis of meningiomas in both NF2-mutated and non-NF2-mutated meningiomas." (PMID 39202270, 2024). "We constructed a BALB/C nude xenograft mouse model in which mice were transplanted with NF2‐associated meningioma cells." (PMID 38828669, 2024). "Overall, the pretrained base machine learning model predicted NF-2 mutations in meningiomas using SWI images with an accuracy that was lower than that for the prediction of S100 protein expression in this limited patient cohort." (PMID 38611661, 2024). "Approximately 50% of meningiomas exhibit NF2 mutations and/or loss of chromosome 22, where NF2 is located." (PMID 39066986, 2024). "In conclusion, this study demonstrated the potential of SWI-based imaging features in predicting S100 protein expression and NF-2 mutations in meningiomas." (PMID 38611661, 2024). "The NF2 (Neurofibromatosis 2) gene encodes for the protein Merlin, is inactivated in around 40 to 60% of meningiomas, and is enriched in higher-grade tumors." (PMID 38571886, 2024). "We also identified the effect of rapamycin on the expression of β‐TrCP in NF2‐associated meningioma cells." (PMID 38828669, 2024). "NF2‐associated meningiomas are often associated with a poor prognosis, with a 2.5‐fold increase in the relative mortality rate compared to that for the condition as a whole." (PMID 38828669, 2024). "In this study, we first determined the infiltrating immune cell populations in NF2‐associated meningiomas." (PMID 38828669, 2024). "This study demonstrated the potential of features extracted from SWI in predicting S100 protein expression and NF-2 mutations in meningiomas." (PMID 38611661, 2024). "Paediatric meningiomas are associated with neurofibromatosis 2 (NF2) representing over 20% of cases encountered." (PMID 39612013, 2024). "MenG B meningiomas were all NF2-deficient, had a low degree of chromosomal instability, and had overall good clinical outcomes, seemingly matching the MG1 and IE groups." (PMID 38695575, 2024).
meningioma (continued). "As NF2 mutations serve as malignant markers of meningioma, FAK inhibition, and NF2 loss have been shown to have a synthetic lethality relationship." (PMID 38410129, 2024). "The sole common thread linking ependymomas and meningiomas (occasionally, medulloblastomas) is the presence of monosomy 22 chromosome, alongside mutations in the NF2 gene located on this chromosome." (PMID 39022728, 2024). "Mutation of NF2 is the most recognized associated gene mutation with atypical meningiomas and is found in up to 75% of such tumors." (PMID 39569229, 2024). "Nevertheless, several genetic driver mutations have been discovered in meningiomas, of which the most prominent one is described for the tumor suppressor gene Neurofibromin-2 (NF2)." (PMID 39273576, 2024). "Several studies of meningiomas and other cancers erroneously equated mutated NF2 with a complete loss of function." (PMID 39796693, 2024). "There is an association of NF2 with an increased number of atypical and anaplastic type meningiomas." (PMID 39612013, 2024). "In conclusion, SWI showed promise in identifying NF-2 copy number loss and S100 protein expression by revealing neovascularization and microcalcification characteristics in meningiomas." (PMID 38611661, 2024). "Our review found that NF2-mutated tumors defined by this Hippo signaling pathway-mediated stem cell regulation include meningiomas, schwannomas, mesotheliomas, breast cancers, hepatocellular carcinomas, renal cell carcinomas, thyroid cancers, and melanomas." (PMID 39796693, 2024). "MG2 meningiomas were found to be enriched for non-NF2 mutations and angiogenic processes, earning the “NF2-wild type” designation." (PMID 38695575, 2024). "Clinical severity of NF2 depends on the type and position of the NF2 alteration, with ependymomas and meningiomas more often arising in patients with truncating NF2 mutations compared to milder clinical phenotypes in patients with missense or mosaic mutations." (PMID 38265489, 2024). "This study aimed to investigate non-invasive biomarkers of NF-2 copy number loss and S100 protein expression in meningiomas using morphological, radiomics, and deep learning-based features of susceptibility-weighted MRI (SWI)." (PMID 38611661, 2024). "EPHA2 shows overexpression predominantly in pediatric CNS tumors and malignancies arising from bone and soft tissues, namely glioma, medulloblastoma cell lines, craniopharyngioma, NF2-deficient meningioma, Ewing sarcoma, and osteosarcoma." (PMID 38612645, 2024). "NF2, a genetic disease associated with bilateral VSs as well as other tumors at various locations (schwannomas, ependymomas, meningiomas), has a prevalence of around 1 in 60,000 people." (PMID 38892775, 2024). "Around half of all meningiomas harbor inactivating mutations in NF2, leading to deregulation of oncogenic YAP1 activity." (PMID 39380691, 2024). "Since the NF2 LOF mutations were all identified in the meningioma patients, we further examined their tumorigenic roles using a malignant meningioma cell line IOMM-Lee." (PMID 39572544, 2024). "Genetic tests have demonstrated that a suppression mutation in neurofibromatosis type-2 (NF-2), an important tumor suppressor gene, is associated with up to 40% of instances of childhood meningioma." (PMID 39156289, 2024). "FD is caused by a mosaic activating pathogenic variant in GNAS gene, and the development of sporadic meningiomas also has genetic predisposition including NF2, TRAF7, KLF4, AKT1 and TERT." (PMID 38287340, 2024). "Monosomy, NF2 mutations, and TRAF7 mutations seem to be the drivers of tumorigenesis in sporadic meningiomas, and as many as 60% of all sporadic meningiomas involve a loss of heterozygosity on chromosome 22 due to inactivating mutations of NF2." (PMID 39796693, 2024). "Most non-NF2 gene meningiomas are usually caused by mutations in SMO (9%) and AKT1 (30%), especially in the cases where the meningioma is at the convexity at the skull-based, respectively." (PMID 39329938, 2024).
meningioma (continued). "Meningiomas with a predilection for the spine are typically found in patients with multiple meningiomas, such as those who harbor a germline mutation in NF2." (PMID 38611105, 2024). "KLF4-K409Q mutations are found in a subset of NF2 wild-type meningiomas and almost always cooccur with mutations in TRAF7." (PMID 38571886, 2024). "When T cells were cocultured with siPD‐L1‐transfected NF2‐associated meningioma cells, the expression of CD69 on both CD4+ and CD8+ T cells was partly reversed, and the capacity of CD8+ T cells to kill siPD‐L1‐transfected tumor cells was partly restored." (PMID 38828669, 2024). "The majority of NF2-SWN-associated meningiomas are asymptomatic and often diagnosed during the work up for NF2-SWN or over the course of routine radiographic surveillance." (PMID 38695575, 2024). "To better mimic NF2‐associated meningioma cells, we established a stable NF2 knockdown cell line by shRNA knockdown (IOMMNF2KD) and a stable 518D overexpression cell line by lentivirus infection (IOMM518D) in IOMM‐Lee cells." (PMID 38828669, 2024). "S100 protein expression levels and neurofibromatosis type 2 (NF-2) mutations result in different disease courses in meningiomas." (PMID 38611661, 2024). "Cancers characterized as having driver mutations in NF2 were meningioma, schwannoma, ependymoma, mesothelioma, and renal cell carcinoma." (PMID 39796693, 2024). "When PD‐L1 levels were downregulated by siPD‐L1 transfection in NF2‐associated meningioma cells, the CCK‐8 assay showed that the tumor cell growth rate was significantly reduced, and both the early and late apoptosis rates were elevated." (PMID 38828669, 2024). "Among these, MG1 meningioma harbours a uniform loss of chromosome 22q and concurrent NF2 point mutations, resulting in biallelic NF2 inactivation." (PMID 38879686, 2024). "Taken together, these findings mechanistically link oncogenic deregulated YAP activity to NF2 loss and meningioma pathobiology." (PMID 38571886, 2024). "Molecular alterations in meningioma have been well-characterized, including characteristic mutations such as NF2, copy number alterations, and DNA methylation signatures and integrated molecular classifications of meningioma have been proposed." (PMID 39682104, 2024). "T cells were separated from HDs, stimulated with Cell Stimulation Cocktail and cocultured with either CFSE‐labeled siPD‐L1‐ or siPD‐L1‐NC‐transfected NF2‐associated meningioma cells." (PMID 38828669, 2024). "The phase II CEVOREM trial (NCT02333565) combined octreotide, a somatostatin analog, with everolimus for the treatment of aggressive and otherwise treatment-refractory meningiomas, although only 4 of the 20 patients had a germline NF2 mutation." (PMID 38695575, 2024). "One molecular group was designated as “immunogenic”, in which meningiomas were characterized by NF2 mutations and the loss of chromosome 22q as well as enrichment in transcriptomic pathways involved in immune signaling and regulation." (PMID 39273576, 2024). "By contrast, NF2-mutated meningiomas are located along the convexity and falx and are often the transitional/fibroblastic subtype." (PMID 38730704, 2024). "22q loss is present in many patients with an established NF2 mutation, and the somatic mutation is present in approximately 47% of sporadic meningiomas." (PMID 39202270, 2024). "NF2 wild-type meningiomas frequently harbor mutations in TRAF7, KLF4, AKT1, PIK3CA, and SMO and are enriched in skull-base meningiomas." (PMID 38571886, 2024). "Neurofibromatosis type 2 (NF2) is a tumor suppressor gene implicated in various tumors, including mesothelioma, schwannomas, and meningioma." (PMID 38879686, 2024). "Chromosome 22q loss encompassing the NF2 gene was present in all tumors along with SCNAs previously reported in Grade 2 and Grade 3 meningioma primary tumors including chr1p, chr6q, chr10, chr14q, chr18p, and q copy number loss." (PMID 39935847, 2024).
meningioma (continued). "As we have confirmed the expression of PD‐L1 in NF2‐associated meningiomas, we next designed siRNAs and silenced PD‐L1." (PMID 38828669, 2024). "Conversely, in a clinical trial of meningioma patients with somatic loss of the neurofibromatosis type II (NF2) gene, FAK inhibitor monotherapy extended progression-free survival at six months in grade 1–3 tumors compared to historical controls." (PMID 39034922, 2024). "Meningiomas with NF2 loss tend to be located along the cerebral convexities or in the posterior/lateral skull base." (PMID 38695575, 2024). "Loss of heterozygosity (LOH) of 1p was associated with chromosome 22/NF2 deletions in meningiomas, and poorer PFS." (PMID 36840836, 2023). "A 2020 study, suggested that high grade/progressive meningiomas be divided into three sub-groups; NF2-associated canonical group, NF2-agnostic group and NF2-exclusive group." (PMID 36882706, 2023). "Neurofibromatosis type 2 (NF2), now termed NF2-related schwannomatosis, is an autosomal dominant disorder that is believed to predispose individuals to the early development of meningioma." (PMID 37628996, 2023). "Although neurofibromatosis type 2 (NF2) is much less common than neurofibromatosis type 1 (NF1), NF2 is more commonly associated with meningiomas, with estimates that 45%–58% of NF2 patients harbor intracranial meningiomas and 20% harbor spinal meningiomas." (PMID 37675219, 2023). "Clinically, carriers with NF2 germline mutations are predisposed to bilateral vestibular schwannomas, those of other cranial and peripheral nerves, meningiomas, and ependymomas." (PMID 37180489, 2023). "MenG C meningiomas were NF2-deficient with associated 1p loss in addition to having a higher burden of other copy number alterations, and clinically were the poorest performers." (PMID 36840836, 2023). "One of the most common molecular alterations in meningioma are mutations in the NF2 gene, which is located on chromosome 22 and functions as a tumor suppressor gene." (PMID 36641486, 2023). "The frequency of intracranial meningiomas was reported to range from 45 to 58%, and the existence of meningiomas in NF2 patients is robustly associated with mortality." (PMID 37752594, 2023). "The mTORC1 signaling is highly activated in NF2-deficient mesothelioma, schwannomas and meningiomas, thereby inducing tumor growth and rapamycin sensitivity." (PMID 37217995, 2023). "As our cohort only included 2 grade 3 meningiomas after radiation and these already had an underlying heterozygous NF2 variant it is unlikely that we would have found an NF2 rearrangement as a second hit." (PMID 37051330, 2023). "Meningiomas are often associated with inactivation of the tumor suppressor NF2/Merlin15, but approximately one-third of meningiomas are Merlin-intact and have favorable clinical outcomes." (PMID 36993679, 2023). "Since molecular alterations of NF2 are frequent in meningiomas, molecular pathways NF2-linked have been studied as possible targets for pharmacotherapy." (PMID 38137885, 2023). "Female gender, convexity/falx and spinal meningioma location as well as NF2 and WHO grade 1 were associated with higher immunopositivity rates for S100 expression." (PMID 35838837, 2023). "The NF2 mutations were present in the pre- and post-progression meningioma from each patient, of note, patient G had three different NF2 mutations in four tumours suggesting separate mutational evolution." (PMID 36882706, 2023). "The most common tumors associated with NF2 are bilateral vestibular schwannoma, meningioma, and ependymoma." (PMID 37217995, 2023). "For this reason, to date, the mutational landscape can be divided into NF2-mutated (approximately 40–60% of cases) and non-NF2-mutated meningioma." (PMID 37760490, 2023). "PIK3CA mutations occur in about 7% of all meningiomas; they are mutually exclusive with NF2 and AKT1 and often associated with TRAF7 mutations." (PMID 38137885, 2023).